NCR1 (natural cytotoxicity triggering receptor 1)
Diseases named in the same sentence as NCR1 in open-access papers (continued):
Sharing a sentence is not in itself a finding about the gene and the disease.
tumor (continued). "With that regard, as we and others previously demonstrated, we now affirm the strong involvement of NKp46 in controlling tumor metastases, as the Ncr1 over expressing mice better control metastases formation." (PMID 29026144, 2017). "For example, NK cells that express a high density of NCR1 showed an increased cytotoxicity against NK sensitive tumor cell lines compared with NK cells expressing lower levels of NCR1." (PMID 27446081, 2016). "NKp46 and Ncr1 are also similar in that sense as the O-glycosylations of NKp46 were also shown to be important for its tumor recognition." (PMID 27462433, 2015). "As NCR1 has been shown to contribute to anti-tumor immunity, in the present work we have explored the use of NCR1 as a targeting moiety to redirect T-cells anti-tumor activity against a panel of different malignancies." (PMID 25431955, 2014). "Previous studies demonstrated that the direct recognition of tumor cells, viral infected cells and beta cells by NKp46 (NCR1) lead to killing and to the secretion of TNF-α and IFN-γ." (PMID 22457623, 2012). "Interestingly, however, the binding of the double and triple mutated Ncr1 fusion proteins to all the cell lines was unchanged or even increased, suggesting that the 3 N-glycosylated residues of Ncr1 play little role in the recognition of the tested tumor cell lines." (PMID 22615821, 2012). "Using Ncr1-driven conditional knockout transgenic mice, which specifically delete Prdm1 in group 1 ILCs, we not only validated Prdm1’s positive regulation of NK cell maturation, but also demonstrated its indispensable role in NK cell anti-tumor activity." (PMID 39133873, 2024). "Bioinformatic analyses revealed five major cell types based on hallmark gene expression: myeloid (Cd11b; 12 clusters), lymphoid (Cd33/Ncr1/B220/Cd19; five clusters), tumor (Olig2/Cd276/Col11a1; one cluster), endothelial (Enpp2; one cluster), and fibroblast (plp1/Ptgds; one cluster) cells." (PMID 37971169, 2023). "Bioinformatic analyses revealed five major cell types based on hallmark gene expression: myeloid (Cd11b; 12 clusters), lymphoid (Cd33/Ncr1/B220/Cd19; 5 clusters), tumor (Olig2/Cd276/Col11a1; 1 cluster), endothelial (Enpp2; 1 cluster) and fibroblast (plp1/Ptgds; 1 cluster) cells." (PMID 37333156, 2023). "Tumor samples with high levels of THBD mRNA (median split) were significantly enriched of CD56dim NK cells in both Nanostring-NB and SEQC-NB cohorts, as well as high levels of NCR1 mRNA were associated with an abundance of intratumoral DCs." (PMID 33239635, 2020). "NKp46 encoded by NCR1 was identified as a pivotal member of NCR family which was specifically expressed on both resting and activated NK cells, acting as a tumor suppressor in tumor growth and metastasis." (PMID 29636640, 2018). "Here, most HPV-positive tumors separated into clusters, mainly due to differences in the expression of immune related proteins on the cell surface of tumor infiltrating immune cells, e.g., PD-1, FasL, NCR1, and KLRD1 or soluble cytokines/chemokines e.g., IL12 and CCL4." (PMID 29587383, 2018). "Also consistent, we observe rescue of BPTF KD tumor growth when NCR1 blocking mAb are used in vivo and is consistent with other reports that NCR1 is important for antitumor activity." (PMID 28969075, 2017). "Specifically, NKp46/Ncr1 was shown to interact with the viral hemagglutinin (HA) protein and with an unknown tumor/cellular ligand." (PMID 27462433, 2015). "It is thus possible that similarly to HAs (the viral ligands of Ncr1), the tumor ligands or co-ligands recognized by Ncr1 might be lectins." (PMID 27462433, 2015). "However, despite years of research, the identity of the cellular/tumor ligand/s recognized by NKp46/Ncr1 is still obscure." (PMID 27462433, 2015). "Yet, despite this powerful, commercially available tool, the tumor and cellular ligand(s) for NKp46/NCR1 remain unknown." (PMID 24478773, 2014).
tumor (continued). "We therefore next tested whether N glycosylation is important for the binding of Ncr1 to mouse tumor cells." (PMID 22615821, 2012). "Alternatively, it is possible that other elements, which are exposed following the removal of the sugars in the mutated Ncr1-Ig protein are responsible for the better binding of the double and triple mutated Ncr1 proteins to PR8 coated and infected cells and to some tumor cells." (PMID 22615821, 2012). "Thus, the loss of CD16, NKG2D and NCR1 does not cause any defect in the ability of NK cells to kill hematopoietic and non-hematopoietic tumor targets in vitro." (PMID 37520575, 2023). "Indeed, NCR1−/− mice underwent a more aggressive tumor development compared to wild type (WT) mice." (PMID 32038612, 2019). "Thus, we speculated that miR-544 was closely related with RUNX3 and NCR1 expression in tumor immune escape." (PMID 29636640, 2018). "In the long-term experiment (21d - tumor cell challenge) DIO fed rats which developed lung metastases had significantly lower relative splenic mRNA concentrations of the activating NK cell receptor NCR1/NKp46 compared to the corresponding control rats receiving NaCl." (PMID 28690853, 2017). "NCR1 expressing NK cells and immature lymphoid cells can control the immune response by direct killing of dendritic cells and T cells, which could suppress an adaptive immune response to 66cl4 tumors, possibly explaining their pro-tumor activities." (PMID 28969075, 2017). "Therefore, to minimize the background staining of Ncr1 Ig to its unknown tumor ligand/s, we used a low fusion protein concentration in which almost no Ncr1 Ig staining was observed." (PMID 27462433, 2015). "The identity of the tumor ligand/s of NKp46/Ncr1 is still unknown." (PMID 27462433, 2015). "EL4 cells express high levels of the unknown Ncr1 tumor ligand." (PMID 27462433, 2015). "Mechanistically, NKp46 recognition of the P domain of ecto-CRT triggers NK cell signaling and enhances tumor-infiltrating NK cell degranulation and cytokine secretion, but the upstream regulators of Ncr1 remain undefined." (PMID 39920136, 2025). "PGE2 inhibits NK cell effector receptors, such as NCR2/NKp44, NCR1/NKp46, NCR3/NKp30, NKG2D, and CD16, leading to impaired function and promoting tumor immune evasion." (PMID 39609700, 2024). "In mouse models, NCR1-mediated IFN-γ production leads to increased expression of FN1 in tumors, thereby altering the primary tumor structure and reducing tumor metastasis." (PMID 38730335, 2024). "Specifically, Kyn inhibits expression of the natural cytotoxicity triggering receptor 1 (NCR1, also known as NKp46) and killer cell lectin like receptor K1 (KLRK1, also referred to as NKG2D) on NK cells resulting in impaired tumor-killing functions." (PMID 37876966, 2023). "The number of cells that were positive for the expression of CD8 and NKp46/NCR1 was significantly increased in the anti-TNFα mAb group, indicating that immunity against the tumor was enhanced in the anti-TNFα mAb group." (PMID 36996146, 2023). "Significantly increased primary tumor staining for CD4, CD8α and NCR-1 as NK(-T) cell marker upon eMSC compared to sham treatment in all operated mice corroborated the flow cytometry results." (PMID 37928528, 2023). "We observed that IV BCG increased the abundance of NCR1+ NK cells and CD8+ T lymphocytes both inside the tumor and at the adjacent tissue." (PMID 37794033, 2023). "In order to determine if the presence of tumor scIgGs impacted NK cell activation and cytotoxicity, we measured granzyme B, perforin, and natural cytotoxicity triggering receptor 1 (NCR1/NKp46/CD335) as molecular signatures of NK cell activation." (PMID 36104515, 2022). "We found that numerous NK cell effector function-related genes, such as TBX21, FYN, NCR1, SH2D1A, SH2D1B, PTPN6, and IL18RAP, were downregulated in tumor-infiltrating NK cells." (PMID 34535671, 2021).
tumor (continued). "Activating cytotoxicity receptors (NCRs), NKp46 (NCR1, CD335), NKp44 (NCR2, CD336), NKp30 (NCR3, CD337), contain immunoglobulin-like domains binding to tumor antigens, viral proteins, and some bacterial components." (PMID 34017328, 2021). "Comparing single groups relative mRNA concentrations of NCR1/NKp46 were significantly decreased in the DIO/NaCl and the DIO/Tumor group compared to animals receiving the control diet and a NaCl-injection." (PMID 33244094, 2020). "To date, CD16, NKG2D, NKp46 (natural cytotoxicity receptor 1; NCR1), DNAM-1, 2B4, NTB-A and CRACC have been found to be critical for tumor surveillance in both human and murine NK cells." (PMID 32290478, 2020). "On the other hand, activating receptors like CD16, NKG2D, NKp46 (natural cytotoxicity receptor 1 (NCR1)), DNAM-1, 2B4, NTB-A, and CS1 have been found to be critical for tumor surveillance in both human and murine NK cells." (PMID 32630303, 2020). "NCR1/NKp46 expression in NK cells was significantly influenced by DIO-diet and tumor cell injection." (PMID 33244094, 2020). "The following hypothetical mechanisms were considered to explain the phenomenon: changes in tumor microvessel formation (CD31), tumor proliferation (Ki67), tumor apoptosis (TUNEL), the NK cell response (NCR1) or the T lymphocyte response (CD8 and CD4)." (PMID 31391111, 2019). "Blocking mouse NCR1 in vivo rescues BPTF KD tumor weights, demonstrating its importance for the control of tumor growth." (PMID 28969075, 2017). "The natural killer (NK) cell activating receptor NKp46/NCR1 plays a critical role in elimination of virus-infected and tumor cells." (PMID 28261217, 2017). "NKp46/NCR1 is an activating receptor involved in the killing of virus-infected, tumor cells and self-cells and in the secretion of IFN-γ and of TNF-α in response to various stimulations." (PMID 22457623, 2012). "Interestingly, Ncr1ΔCxcr3 mice displayed increased metastasis incidence at 15 days and increased tumor burden at 20 days postinjection, indicating a role for CXCR3+NKp46+ cells in protection from metastasis." (PMID 40168086, 2025). "Along this line, blockage of NKp46 leads to the inhibition of NK cell-mediated killing of diverse cancer targets, and in the absence of Ncr1, mice displayed impaired tumor immunosurveillance." (PMID 39920136, 2025). "The Ncr1gfp/gfp mice exhibited significantly more tumor growth and their spleens, but not their livers, were enlarged when compared to the Ncr1+/+ mice." (PMID 39856052, 2025). "NCR1 is a receptor that recognizes tumor cells in a non-major histocompatibility complex-restricted manner, which activates NK cells and kills tumor cells." (PMID 38891037, 2024). "Additionally, the TLS density was significantly positively correlated with CD4+ T cells, CD8+ T cells, CD20+ B cells, CD45RO+ memory T cells and NCR1+ NK cells and negatively correlated with CD15+ TANs in the tumor centre." (PMID 38322490, 2024). "Of note, conditional knock-out mice based on Ncr1-cre deletion not only affects NK cells but also ILCs (ILC1 and NCR+ ILC3), therefore it is likely that ILCs contribute to anti-tumor responses, although this requires more specific depletion of ILC1s to establish their direct role." (PMID 38567059, 2023). "Among others, germline-encoded activating receptors, such as KLRK1 (also known as NKG2D) and the Natural cytotoxicity receptors (NCRs), such as NKp46 (NCR1), NKp44 (NCR2), and NKp30 (NCR3), can synergize to overcome inhibitory thresholds and evoke NK cell anti-tumor functions." (PMID 34539622, 2021). "However, experimental studies of CD244, NCR1, and NCR2 showed that knocking them down in NK cells affected tumor surveillance or metastasis (eTable 6 in the Supplement)." (PMID 31483464, 2019). "Furthermore, we have recently shown that deletion of a single NCR gene, the NKp46 mouse homologue (NCR1), significantly reduces the ability of NK cells to clear tumor cells in vivo." (PMID 18478075, 2008).
tumor (continued). "In tumor tissues with a high SIGLEC1/CD68 ratio, there was an increase in the infiltration and function of cytotoxic lymphocytes, based on the expression of the T cell receptor CD3 complex subunit (CD3E), natural cytotoxicity receptor (NCR1), and interferon gamma (IFNG)." (PMID 36266311, 2022). "Moreover, NCR1 and other NK cell activating receptors (such as NKG2D) could contribute to protection against auto-immunity or to tumor immune escape." (PMID 34576181, 2021). "Unlike in NK cells in which NCR1 can be down-regulated in cancer patients and its activity could be attenuated when exposed to tumor-expressed inhibitory ligands (such as MHC), T-cell expressing N1/28z could circumvent such an inhibition." (PMID 25431955, 2014). "A possible explanation to this observation is that the mouse BW cells express an unknown tumor ligand for the mouse NCR1 which consistently triggers IL-2 secretion as BW cells are specifically recognized by NCR1-Ig (data not shown)." (PMID 22457623, 2012). "The various Ncr1-Ig fusion proteins were incubated with PR8-coated 721.221 cells that were used because the 721.221 cells do not express tumor ligands for Ncr1 and because the adherence of the virus and the consequent Ncr1-Ig recognition is efficient in this cell line." (PMID 22615821, 2012). "The binding of the wild type Ncr1 fusion proteins produced either in COS-7 cells, or in HEK293T to the various cell lines was heterogeneous, probably reflecting the different levels of the unknown Ncr1 tumor ligand(s) on the various cell lines." (PMID 22615821, 2012). "However, tumor cells did not express CD335 (NKp46; Ncr1), a marker of active NK cells." (PMID 28692033, 2017).
infection (100 papers, 2009 to 2025). The state of being infected such as from the introduction of a foreign agent such as serum, vaccine, antigenic substance or organism. "The IL-10-deficient NK cell Ncr1-iCre-Il10fl/fl mouse strain and wt B6 mice were infected with Lm peroral (PO) or coinfected with S. pneumoniae intratracheal (IT) + Lm PO, and the spleens, livers, and lungs were harvested at 3 days post-infection." (PMID 35053151, 2021). "Finally, they found murine alveolar bone loss in the presence of natural cytotoxicity triggering receptor 1 (NCR1) after infection with Fusobacterium nucleatum." (PMID 33371393, 2020). "Alternatively, since inflammation contribute to S. pneumoniae proliferation in lungs and NK cell activity and IFNγ could enhance inflammation, the lesser contribution of NCR1-deficient NK cells to inflammation could oppose the picture in the later stages of the infection." (PMID 21887255, 2011). "NCR1+ NK cells represented only a small proportion of the total intranasal immune cells, decreased by day 6pi (p = 0.006), and returned to pre-infection percentages by day 14pi." (PMID 39459849, 2024). "The M2 infection module revealed Chil3, Il4, Cx3cr1, Emr1 and Ccl2 as hubs, while module M6, associated with vaccination, disclosed Prf1, Klrc1, IFN-γ, Ncr1 and Tbx21 as hub proteins." (PMID 39563428, 2024). "The present data supplements the findings by showing that besides lower activity in the periphery, SJL mice also have lower absolute numbers of NCR1+ NK cells in the brain during early stages of TMEV‐infection." (PMID 34231271, 2021). "Following TMEV‐infection, multifocal groups of NCR1+ cells with lymphocyte morphology and a distinct membranous immunostaining were detected in B6 mice (Figure 5A1)." (PMID 34231271, 2021). "In contrast to non-vaccinated mice, however, vaccination-protected mice respond to infection with a significantly higher expression of Ncr1 on day 1 p.i." (PMID 33202767, 2020). "Our new mouse model is suitable to further address the role of Ncr1+ cell-derived IFN-γ also in other models of infection, as well as of autoimmunity and cancer." (PMID 32023327, 2020). "Our data show a novel pathway employed by NK cells to regulate antiviral CD8 T cell responses, namely direct recognition and elimination of activated CD8 T cells via NCR1 early during infection to protect the host from an overshooting T cell response." (PMID 30995287, 2019). "Upon LCMV infection, total numbers of endogenous CD8 T cells were increased in absence of NCR1, both in NCR1gfp/gfp mice and in C57BL/6 mice upon in vivo blocking of NCR1, using an αNCR1 antibody (ab) during infection." (PMID 30995287, 2019). "The fraction of cells expressing IL2 receptor (CD25), higher in the NCR1+/CD8+ population than among the CD8+/NCR1- cells in jejunal Peyer’s patches, remained unchanged during infection." (PMID 25890354, 2015). "We first aimed to evaluate the influence of deficiency of the activating natural killer cell receptor gene, Ncr1, on the survival of mice after infection with S. pneumoniae." (PMID 21887255, 2011). "Lower lethal doses did not induce differences in survival rate; yet, during the first 6 hours of infection, a significantly reduced bacterial load was observed in the lungs of Ncr1+/+ and Ncr1+/gfp mice compared to Ncr1gfp/gfp mice." (PMID 21887255, 2011). "The reduced bacterial load in the Ncr1+/+ and Ncr1+/gfp mice suggested that the NK cell were activated via NCR1 following infection." (PMID 21887255, 2011). "In contrast, 3h following infection, TNFα and IL-6 transcripts in the lungs of Ncr1gfp/gfp mice were significantly higher compared to the transcripts of these cytokines in Ncr1+/gfp mice." (PMID 21887255, 2011). "In accordance with the CD107a levels, 3h following infection the IFNγ transcript level in the lungs was significantly higher in Ncr1+/gfp mice compared to Ncr1gfp/gfp infected mice." (PMID 21887255, 2011).